SOX8 (SRY-box transcription factor 8)
Diseases named in the same sentence as SOX8 in open-access papers (continued):
Sharing a sentence is not in itself a finding about the gene and the disease.
heart failure (2 papers, 2023 to 2024). Inability of the heart to pump blood at an adequate rate to meet tissue metabolic requirements. "Additionally, a moderate to strong association of the RNA level of SOX4/SOX8 with fibrotic genes was observed, and via a meta-analysis of epigenetics and whole-genome association data, several genomic variants accountable for heart failure were linked to SOX4 or SOX8." (PMID 39518344, 2024). "It is reported that SOX8 proteins were markedly increased in patients with heart failure." (PMID 37828521, 2023).
melanoma (2 papers, 2018 to 2022). A malignant, usually aggressive tumor composed of atypical, neoplastic melanocytes. "Supporting the results from the melanoma cell lines, we found increased expression of SOX9 and loss of expression of SOX2, SOX5, and SOX8, suggesting that SOX10KO cells reverted to a pre-NC state." (PMID 36040798, 2022). "In comparison, the SOX10+MITF– NCSC-like melanoma cell lines had acquired expression of other NC-derived lineage markers such as SOX2 (expressed in glial lineages), SOX5, and SOX8 (expressed in neural progenitors)." (PMID 36040798, 2022). "Furthermore, IPA protein-protein interaction (PPI) analysis for co-module #12 showed that melanoma-related transcription factors, such as MITF, PAX3, SOX8, and SOX10, formed a sub-network." (PMID 29950679, 2018).
pancreatic cancer (2 papers, 2022 to 2025). "In order to verify the expression of SOX8 in pancreatic cancer, we collected postoperative specimens of 257 PDAC patients and performed IHC staining." (PMID 35173526, 2022). "The results showed that the expression of SOX8 in pancreatic cancer was significantly higher than that of normal pancreatic tissue." (PMID 35173526, 2022). "According to the expression level of SOX8 in each pancreatic cancer cell line, we constructed stable SOX8 overexpressing Panc-1 cell line (Panc-1 SOX8) and Sox8 knockdown CFPAC-1 cell line (CFPAC-1 shSOX8)." (PMID 35173526, 2022). "SOX8 transcriptionally regulated EZH2, which reduced expression of SPARC by promoting the methylation of SPARC, thereby reducing the transport of albumin-bound paclitaxel in pancreatic cancer cells." (PMID 35173526, 2022).
Testicular regression syndrome (2 papers, 2023 to 2025). Testicular regression syndrome (TRS) is a developmental anomaly characterized by the absence of one or both testicles with partial or complete absence of testicular tissue. "More recently, a novel heterozygous missense mutation in SOX8 was identified in a 46,XY female patient with testicular regression syndrome, providing further evidence of SOX8's involvement in human reproduction." (PMID 39936824, 2025). "A novel heterozygotic p.T226P variant in SOX8 gene was identified in a 46,XY female with probable testicular regression syndrome (high FSH, LH levels, no residual gonad, absent vagina and uterus)." (PMID 36631813, 2023).
Azoospermia (1 paper, 2022). Absence of any measurable level of sperm,whereby spermatozoa cannot be observed even after centrifugation of the semen pellet. "In Chinese males, harmful mutations in the SOX8 gene may not be a prevalent cause of oligo/azoospermia." (PMID 36071829, 2022).
cerebellar tumors (1 paper, 2018). "SOX8 is expressed in immature glia of the developing cerebellum and in cerebellar tumors and has important functions in oligodendrocyte development and differentiation." (PMID 29631562, 2018).
cryptorchidism (1 paper, 2018). The failure of one or both testes of a male fetus to descend from the abdomen into the scrotum during the late part of pregnancy. "Indeed, 46, XY individuals carryingdeletions that include SOX8 (ATR16 syndrome) occasionally present with mildanomalies such as hypospadias or cryptorchidism and Patients 1 and 2 may represent part ofthis broad DSD spectrum." (PMID 29373757, 2018).
diffuse astrocytoma (1 paper, 2020). A low-grade (WHO grade II) astrocytic neoplasm. "Additionally, the low‐grade diffuse astrocytomas and oligodendroglial tumors are associated with particularly high SOX8 expression." (PMID 32307911, 2020).
endometrial carcinoma (1 paper, 2021). A malignant tumor arising from the epithelium that lines the cavity of the uterine body. "Similarly, higher SOX8 expression is linked to a high tumor histological grade, lymph node metastasis, and shorter overall survival in patients with endometrial carcinoma." (PMID 34090518, 2021).
gouty arthritis (1 paper, 2023). "Meanwhile, the dramatically increased expressions of Beclin1 and the ratio of LC3-II/I in acute gout models were ameliorated by overexpression of Sox8." (PMID 36918540, 2023). "The findings not only underlie the mechanisms MSU induced cartilage damage, but suggest that Sox8 may serve as a potential drug in the treatment of MSU joint impairment in gout patients." (PMID 36918540, 2023).
growth disorders (1 paper, 2021). "Interestingly, multiple sox family members (sox5, sox6, sox8, and sox18) were significantly dysregulated in shox-deficient pectoral fins together with other genes (nppa, nppc, cdkn1a, cdkn1ca, cyp26b1, and cy26c1), highlighting an important role for these genes in shox-related growth disorders." (PMID 34122528, 2021).
ischemic stroke (1 paper, 2025). A stroke disorder caused by obstruction of blood flow to the brain, due to thrombotic (local blood clot formation) or embolic (due to a blood clot or other material traveling from another site) event. "Our findings suggest that core transcription factors such as SOX8, KLF13, and FOXK1 may serve as crucial therapeutic targets for electroacupuncture in ischemic stroke." (PMID 40109665, 2025). "Furthermore, core transcriptional regulatory circuitries involving SOX8, FOXK1, and KLF13 were identified, highlighting their roles in the modulation of SE-mediated gene regulation by acupuncture in the ischemic stroke context." (PMID 40109665, 2025).
metastatic disease (1 paper, 2026). "Our dada not only identifies a novel circPOLK/miR-1204/SOX8 signaling pathway, but also provides therapeutical strategies for NSCLC patients with metastatic disease." (PMID 42104439, 2026).
pancreatic ductal adenocarcinoma (1 paper, 2022). An infiltrating adenocarcinoma that arises from the epithelial cells of the pancreas. "Collectively, our data revealed SOX8/EZH2/SPARC signaling induced primary chemo-resistance of albumin-bound paclitaxel in pancreatic ductal adenocarcinoma." (PMID 35173526, 2022).
primary ovarian failure (1 paper, 2020). Absent or premature cessation of ovarian function due to a pathologic process originating within the ovaries. "SOX8 mutations were found more frequently in oligozoospermic men (3.5%; p < 0.05) and in primary ovarian failure (5.06%; p = 4.5 × 10−5) compared to fertile/normospermic control populations (0.74%)." (PMID 33158283, 2020).
renal hypoplasia (1 paper, 2021). Renal hypoplasia is a developmental anomaly in which one or both kidneys (unilateral or bilateral renal hypoplasia, respectively) have a deficit in the number of nephrons and may be small. "It was found that the deletion of Sox8 and Sox9 during renal embryonic development led to renal hypoplasia in mice." (PMID 34215331, 2021).
tumor (26 papers, 2018 to 2025). "K‐M analysis revealed that high SOX8 expression was related to the poorer prognostic outcomes and more aggressive tumor progression, indicating that SOX8 increased the TSCC susceptibility." (PMID 32307911, 2020). "SOX8 has been suggested to potentially function in an oncogenic manner, driving tumor development and progression." (PMID 39936824, 2025). "Previous studies have mainly highlighted the roles of SOX8 in various physiological and pathological processes, such as chemotherapy resistance, tumor development, reproductive system development, and nervous system development." (PMID 40918640, 2025). "The clinical relevance of our experimental findings was supported by immunohistochemical staining analyses demonstrating that the expression of HDAC7, ITGB1, LGALS3 and CD44 was highest in GBM tumours and was negatively correlated with SOX8 expression." (PMID 39629136, 2024). "SOX8 is a member of the sex determining region Y-boxes family, which is potentially related to the chemoresistance of tumor." (PMID 35173526, 2022). "SOX8 was found to be expressed in 44% of TNBC samples (out of 250 samples) and was positively and significantly associated with tumour size and stage." (PMID 35267409, 2022). "To directly determine if SOX8 alters albumin uptake in tumor cell lines, we added Nab-p to control, SOX8 overexpression and SOX8 knockdown cells and performed immunoblotting with a human specific primary antibody to albumin." (PMID 35173526, 2022). "Conversely, SOX8 is highly overexpressed in FP-RMS tumours, and SOX8 disruption leads to upregulation of MYOD1 and MYOG in FP-RMS, suggesting a negative regulatory mechanism." (PMID 32634370, 2020). "For confirming the role of SOX8 in regulating the growth of TSCC tumor in vivo, the TSCC xenograft nude mouse model was constructed." (PMID 32307911, 2020). "Sox8 is highly expressed in many tumor cells, and downregulation of Sox8 suppresses tumor cell proliferation." (PMID 30275866, 2018). "To explore the mechanism by which SOX8 affect sensitivity to Nab-p treatment in PDAC, we tested whether SOX8 would affect albumin uptake in tumor cell." (PMID 35173526, 2022). "Our findings suggest that a high expression of SOX8, Notch4, and Hes5 could lead to tumor metastasis." (PMID 36246971, 2022). "Also, effects of GOLPH3 knockdown and SOX8 over‐expression on Ki67 (a vital factor indicating tumor growth) expression in xenografts was investigated." (PMID 32307911, 2020). "Finally, our study confirms high SOX8 expression in TSCC tumor tissues compared with that in adjacent non‐tumor counterparts, which shows positive correlation with GOLPH3 over‐expression and poor survival." (PMID 32307911, 2020). "Additionally, this study also confirmed SOX8 effects on enhancing tumor progression and growth in vivo, and GOLPH3 participated in the biological process of SOX8 in TSCC." (PMID 32307911, 2020). "Collectively, these results indicated that SOX8 promoted TSCC tumor growth via GOLPH3." (PMID 32307911, 2020). "Moreover our results suggested that the SOX8 level was increased within tumor tissue compared with that in para‐cancer normal counterpart, which showed positive correlation with the GOLPH3 level." (PMID 32307911, 2020). "Our results indicated that GZZSZTW significantly increased the expression levels of multiple genes involved in promoting cell proliferation, most of which are highly expressed in tumor cells, such as Tnfaip2, Chi3l1, Tnf, Pfkfb3, Sox8, Jag1, Mafb, Pla2g7, Hnrnpa1, and E2f3." (PMID 30275866, 2018). "Furthermore, the expression of SOX8 gradually decreased with tumour progression." (PMID 39629136, 2024). "LGALS3 regulated by SOX8/JUN complex was secreted by GSC into the tumour microenvironment, which could not only promote GBM MES transition by binding membrane protein ITGB1 on GSC in an autocrine form, but also promote immunosuppression by binding ITGB1 on TAM in a paracrine manner." (PMID 39629136, 2024).
tumor (continued). "Following SOX8 knockdown, TSCC cells become responsive to cisplatin treatment and lose their ability to form tumor spheres." (PMID 39936824, 2025). "Eight genes were differentially expressed at both the mRNA and protein levels, with ASCL1, EDNRB, INSM1, SOX11, SOX4, SOX8, and SIX1 showing reduced expression in tumor tissues, and CTNNB1 showing increased expression compared with para-cancer tissues." (PMID 40771813, 2025). "We found that HDAC7 facilitated a pro-tumour microenvironment by promoting the malignancy of GSCs and immunosuppressive transformation of MDMs by catalysing histone H3K27 deacetylation of SOX8 promoters to inhibit its expression." (PMID 39629136, 2024). "In our study, we found that SOX8, another SOX gene family member, is also a master positive regulator of PN-like GBM and a negative regulator of MES-like GBM, with both tumour cell intrinsic and microenvironmental effects." (PMID 39629136, 2024). "We observed statistically significant differences in the expression of SOX6, SOX8, SOX21 and SOX30 genes in healthy tissue vs. primary tumor samples." (PMID 38132438, 2023). "Our results clearly point to SOX6, SOX8 and SRY as factors which are characteristic for a tumor tissue." (PMID 38132438, 2023). "We demonstrated statistically significant differences in expression between normal and primary tumor tissues for SOX6, SOX8, SOX21 and SOX30 genes and pointed to SOX6 as the one that met the independent diagnostic markers criteria." (PMID 38132438, 2023). "At last, we found that both SOX8 knockdown and/or RO0429097 suppressed tumor growth and bone metastasis in vivo." (PMID 36246971, 2022). "We found expression of SOX8 was low in PDX0001 and PDX0037 while high in PDX0015 and PDX0049 and the same trend appears in PDX tumor tissues." (PMID 35173526, 2022). "Subcutaneous tumor formation was performed in nude mice with PDX0015 line, which showed a high level of SOX8 expression." (PMID 35173526, 2022). "According to the results of double staining immunohistochemistry, there was high SOX8 and GOLPH3 expression in tumor tissues from TSCC patients relative to adjacent non‐cancer counterparts." (PMID 32307911, 2020). "Furthermore, the SOX8 and GOLPH3 mRNA levels were obviously up‐regulated within TSCC tumor tissues relative to those within matched non‐cancer counterparts." (PMID 32307911, 2020). "Additionally, SOX8 was upregulated in tumor tissues in comparison to a non-cancerous control, which again correlated with GOLPH3 levels." (PMID 38132438, 2023).
cancer (24 papers, 2013 to 2025). A tumor composed of atypical neoplastic, often pleomorphic cells that invade other tissues. "This section will discuss some unique functions of Sox8 from development to adulthood, while its roles in the nervous system, sex determination, and cancer will be covered in more detail in separate sections." (PMID 39936824, 2025). "Understanding SOX8’s contributions to chemoresistance can aid in developing new therapeutic strategies to enhance chemotherapy effectiveness and improve cancer patient outcomes." (PMID 40460162, 2025). "SOX8 is abundantly expressed in multiple cancers, such as tongue squamous cell cancer and CRC, and is associated with poor prognostic outcomes." (PMID 36373629, 2023). "The most significant DMRs associated with gene expression changes, include several cancer-related genes such as KLF10, GSTP1, MEGF10, SOX8 and IRX116–28." (PMID 34997020, 2022). "Recently, SOX8 has been shown to be highly expressed in several cancers, and has been shown to be a potential oncogene." (PMID 32411596, 2020). "SOX8 exhibits low expression in normal adult human tissues, and has recently been proven to be a potential oncogene in several cancers, despite its function in the regulation of drug resistance still remains poorly understood." (PMID 32411596, 2020). "Sox8 might be a promising potential therapeutic candidate, particularly for regenerative and cancer treatments." (PMID 39936824, 2025). "Notably, SOX8 has been identified as a gene of interest in a variety of disorders and its regulatory roles extend from cancer stem cell properties to chemoresistance." (PMID 39936824, 2025). "Overall, evidence suggests that SOX8 could be a promising target for treating drug-resistant cancers, as it appears to play a significant role in promoting chemoresistance." (PMID 39936824, 2025). "SOX8 has been identified as a possible target for treating chemotherapy-resistant cancers." (PMID 39936824, 2025). "However, the limited number of studies on SOX8 in cancer underscores the need to broaden our understanding of its potential as an oncogene with therapeutic interest." (PMID 39936824, 2025). "SOX8 appears to regulate cancer stem cell-like properties by different mechanisms." (PMID 39936824, 2025). "Some in vitro studies have reported altered protein function, and overexpression of SOX8 has been linked to negative outcomes in cancer." (PMID 39936824, 2025). "Consequently, SOX8’s regulation and significance in cancer are very complex and should be explored in future investigations." (PMID 38611002, 2024). "The up‐regulation of SOX2, SOX4, SOX5, SOX8, SOX9 and SOX18 are found to be associated with poor outcome in different cancer types; however, the up‐regulation of SOX11 and SOX30 is favourable for the prognosis in other cancer types." (PMID 32363730, 2020). "However, the regulatory role of SOX8 on drug resistance of cancer cells still awaits further investigation." (PMID 32411596, 2020). "Analyses of transcripts altered in TMED3 kd cells over control levels revealed a group of 63 RNAs enhanced twofold or more that included several genes previously shown to promote pro-metastatic behavior in different cancers, including SOX8, ASCL2, FGF19, and CXCR4." (PMID 31253868, 2019). "SOX8 is critical in developing chemoresistance in cancer cells by regulating gene expression, promoting EMT, maintaining cancer stem cell properties, and modulating apoptotic pathways." (PMID 40460162, 2025). "SOX8 was significantly upregulated in HCC and its upregulation promoted cancer cell proliferation in HCC." (PMID 35465267, 2022). "In recent years, more and more scholars have focused on cancer-related molecular markers and gene targets, such as PAK1 and SOX8." (PMID 36230738, 2022). "In the present study, we found that PDAC patients with high SOX8 expression exhibited poor response to albumin-bound paclitaxel chemotherapy through cohort study and validation of our hospital PDAC cancer tissue." (PMID 35173526, 2022).
cancer (continued). "According to immunoblotting analysis, SOX8 and GOLPH3 protein expression was dramatically up‐regulated within TSCC tissues compared with that in matched para‐cancer counterparts." (PMID 32307911, 2020). "The structure and genomic organization of SOX8 are analogous to those of SOX9, a gene that is also over‐expressed in numerous cancers." (PMID 32307911, 2020). "The overexpressing h-jou transfected cells were also enriched in potential cancer stem cell (CSC) markers, including SOX4, SOX8, CD44, MSI-2, EpCAM, and others." (PMID 33225905, 2020). "Additionally, several studies have highlighted the role of SOX8 in augmenting EMT and drug resistance in cancers." (PMID 36373629, 2023). "SRY-box transcription factor 8 (SOX8), a member of the SOX-E group in the SOXs family, is found to be widely expressed in both embryonic and mature brain tissues and participates in cancer progression." (PMID 36373629, 2023).
degenerative diseases (1 paper, 2023). "In conclusion, our report opens many questions regarding Sox8, not only in MS but other degenerative diseases." (PMID 38097655, 2023).
SOX8 also shares sentences with these, for which no sentence is quoted: cervical cancer (3 papers); lung carcinoma (2); neuroblastoma (2); oligodendroglioma (2); α-thalassaemia (2); adolescent idiopathic scoliosis (1); Alpha-thalassemia (1); campomelic dysplasia (1); colon cancer (1); demyelinating disease (1); developmental delay (1); Hyperinsulinemia (1); hypertrophic cardiomyopathy (1); hypospadias (1); infection (1); lymph node metastasis (1); medulloblastoma (1); microcephaly (1); muscle disorders (1); neurological disorders (1); Obesity (1); oesophageal cancer (1); oligodendroglial tumor (1); Osteopenia (1); ovarian insufficiency (1); ovarian tumours (1); Rb (1); squamous cell carcinoma (1); Uterine leiomyoma (1).